OR8G1 (olfactory receptor family 8 subfamily G member 1)
Description:
Odorant receptor.
Synonyms: OR8G1P; TPCR25; HSTPCR25
Tractability: Antibody: UniProt places it where antibodies can reach, with medium confidence; UniProt predicts a signal peptide or a membrane-spanning region; its Gene Ontology location is reachable by antibodies, with medium confidence.
Gene: Protein-coding gene on chromosome 11 (124,241,095 to 124,254,364, forward strand). Ensembl gene ENSG00000197849.
Subcellular location: Cell membrane
Pathways (Reactome):
Sensory Perception: Expression and translocation of olfactory receptors
Gene Ontology:
Molecular function: protein binding; olfactory receptor activity; G protein-coupled receptor activity
Biological process: G protein-coupled receptor signaling pathway; sensory perception of smell; detection of chemical stimulus involved in sensory perception of smell
Cellular component: membrane; plasma membrane
Genetic constraint (gnomAD): Missense variants: 356 observed, 360.45 expected, observed/expected ratio (o/e) 0.99, 90% interval 0.9 to 1.08. Synonymous variants: 120 observed, 132.49 expected, observed/expected ratio (o/e) 0.91, 90% interval 0.78 to 1.05.
Homologues: Orthologues: mouse Or8g23 (78% identical), rat Or8g20 (77% identical), rat Or8g23 (77% identical), mouse Or8g20 (77% identical), rat Or8g20b (75% identical), mouse Or8g21 (74% identical), rat Or8g21 (73% identical), mouse Or8g28 (72% identical), rat Or8g26 (72% identical), mouse Or8g17 (71% identical), mouse Or8g26 (71% identical), rat Or8g20e (71% identical), and 15 more. Paralogues in human: OR8G5 (85% identical), OR8G3 (77% identical), OR8G2P (74% identical), OR8B3 (66% identical), OR8B2 (65% identical), OR8B8 (64% identical), OR8D1 (63% identical), OR8A1 (63% identical), OR8D2 (62% identical), OR8B12 (61% identical), OR8D4 (60% identical), OR8B4 (58% identical), and 84 more.
Diseases named in the same sentence as OR8G1 in open-access papers:
OR8G1 is named in the same sentence as 1 disease in open-access papers, as found by Europe PMC text mining. Sharing a sentence is not in itself a finding about the gene and the disease.
OR8G1 shares sentences with these, for which no sentence is quoted: pancreatic cancer (1 paper).